KRAS (KRas proto-oncogene, GTPase)
Diseases named in the same sentence as KRAS in open-access papers (continued):
Sharing a sentence is not in itself a finding about the gene and the disease.
colorectal cancer (continued). "Amongst known driver mutations, activating mutations in the KRAS or KRAS2 (Kirsten rat sarcoma virus 2 homolog) oncogene are found in several malignancies including colorectal cancer (CRC)." (PMID 35200357, 2022). "A major determinant ​of panitumumab and cetuximab treatment in colorectal cancer is the presence of mutations in the KRAS gene." (PMID 35619874, 2022). "Although we describe how mutant KRAS regulates the intracellular and extracellular transcriptomes in the context of lung cells, KRAS mutations are also prevalent in pancreatic and colorectal cancer cells." (PMID 35858545, 2022). "The over-activated KRAS is also associated with the functional attenuation of cytotoxic T cells and antitumor neutrophils in patients with colorectal cancers." (PMID 36172359, 2022). "In conclusion, colorectal cancer with a residual adenoma component showed indolent clinicopathologic features and frequent KRAS mutations." (PMID 36083889, 2022). "The KRAS mutation is a relatively early event in colorectal cancer carcinogenesis because this mutation has been identified in adenomas and even in non-neoplastic hyperplastic conditions." (PMID 36083889, 2022). "According to studies, the prevalence of KRAS mutation in colorectal cancer is about 40%, and KRAS mutation suggests poor prognosis." (PMID 36544770, 2022). "The chip can also be used to detect clinical diseases such as KRAS mutations using cfDNA extracted from plasma specimens of patients with non-small-cell lung and colorectal cancer." (PMID 35484481, 2022). "KRAS mutations drive immunosuppression and immunotherapy resistance in colorectal cancer through the IRF2-CXCL3-CXCR2 axis." (PMID 36176287, 2022). "In colorectal cancer cell lines, KRAS copy number gains have been associated with an 11-fold increase in RAS-GTPase activity; similarly, KRAS codon 12 or 13 mutations lead to a 12-fold increase in RAS-GTPase activity." (PMID 35565354, 2022). "Two patients’ tumors had KRASG12D mutations, whereas the remaining 2 patients harbored colorectal cancers expressing wild-type KRAS." (PMID 36382087, 2022). "The surprising discovery of this research is that atypical KRAS mutation G12R, which is relatively rare (~1% in lung and colorectal cancers, ~20% in PDAC), has unique properties in driving macropinocytosis." (PMID 35154489, 2022). "KRAS mutation status had been considered an important prognostic and predictive biomarker for colorectal cancer patients." (PMID 36294412, 2022). "In parallel, in preclinical models of KRAS-mutated colorectal cancer, the combination of ascorbate and chemotherapy improved tumour regression, and this response depended on SVCT-2 expression in tumour cells." (PMID 35744943, 2022). "Jang and colleagues found that 61.8% of colorectal cancers with high-grade tumor budding harbor more KRAS mutations." (PMID 35096426, 2022). "In contrast, PIK3CA mutations are encountered in colorectal cancers with either KRAS or BRAF mutations with an equal or higher prevalence than in cancers with wild type KRAS and BRAF." (PMID 36295658, 2022). "It is well known that mutations in KRAS play a critical role in metabolic reprogramming in multiple cancers, including lung cancer and colorectal cancer." (PMID 36550998, 2022). "Another experiment in colorectal cancer has shown a panel of miRNAs that precisely discriminate KRAS-mutated colorectal cancer tissues from other samples." (PMID 35139853, 2022). "CMS3 is associated with a KRAS mutation associated with resistance to platinum chemotherapy commonly used in colorectal cancer." (PMID 35267605, 2022). "KRAS mutations occur early in the development of colorectal cancer (CRC) and are strongly associated with resistance to therapies." (PMID 35200357, 2022). "The 41.8% KRAS mutation rate and prevalence of G12D/V mutations in small cancer was similar to that in colorectal cancer." (PMID 35359599, 2022).
colorectal cancer (continued). "We designed HSSP to recognize KRAS mutations in the DNA of colorectal cancer tissues (HSSP-G12D (GGT→GAT) and HSSP-G13D (GGC→GAC)) by integration with real-time PCR." (PMID 36004993, 2022). "Both BRAF and KRAS are oncogenes that are commonly mutated in colorectal cancer, and mutations in these genes are often considered mutually exclusive." (PMID 35383926, 2022). "Ethnicity has been proven to play a big role in influencing the prevalence of KRAS mutations, especially in colorectal cancer and lung adenocarcinoma." (PMID 36004014, 2022). "The G12C is the highest KRAS mutation in NSCLC, while the G12D is the highest KRAS mutation in colorectal cancer." (PMID 36614109, 2022). "KRAS mutation is a frequent oncogenic alteration in a broad range of cancer types, including pancreatic cancer (> 80%), colorectal cancer (> 30%), lung cancer (> 30%), cholangiocarcinoma (> 30%), as well as GC (< 10%)." (PMID 36105076, 2022). "KRAS showed a decreased mutation frequency in colorectal cancer patients with ERBB2 amplification compared with non-ERBB2 amplification (15% vs. 49%)." (PMID 35911441, 2022). "Another case where there is now a strong incentive to explore the possible involvement of iRhom2 is colorectal cancer, the second leading cause of cancer-related deaths worldwide, which can also be driven by oncogenic KRAS mutations." (PMID 35971826, 2022). "Few studies have addressed the prevalence and prognostic impacts of KRAS mutations in Saudi patients with colorectal cancer (CRC)." (PMID 35505757, 2022). "In colorectal cancer patients with different KRAS mutations, KRASG13D shows some sensitivity to anti-EGFR cetuximab, albeit less than wild-type did." (PMID 36145664, 2022). "Based on multiple logistic regression model, CEA level, vascular invasion, pT4, pN+, and KRAS mutation were independent risk factors for MLM of colorectal cancer." (PMID 35279173, 2022). "This study observed that the proportion of KRAS G12C mutations in colorectal cancer and non-small cell lung cancer samples was higher in whites than in Asians." (PMID 35359599, 2022). "Low B3GNT6 mRNA levels were significantly associated with chromosome instability (CIN) and KRAS mutations in patients with colorectal cancer." (PMID 35387659, 2022). "Although we found downregulation of both glycosylases and significantly lower expression of hOGG1 in tumor tissues, accompanied with G>T mutations in KRAS gene, oxidative DNA damage and its repair cannot solely explain the onset of sporadic colorectal cancer." (PMID 35628513, 2022). "KRAS G12C, C12V, and G12D variants were detected at resistance time point only or increased in three colorectal cancer patients who were treated with cytotoxic chemotherapy." (PMID 35402275, 2022). "In KRAS-mutated colorectal cancer, combination of MEK and CDK4/6 inhibitors provided a synergistic antitumor activity, both in vitro and in PDX models." (PMID 35712501, 2022). "This patient with a stage IV colorectal cancer was deceased soon after this last blood collection in which the KRAS G60D mutation was identified." (PMID 36579573, 2022). "The epidermal growth factor receptor (EGFR) is a major therapeutic target in colorectal cancers, and the KRAS mutation test is essential in clinical practice for predicting resistance to EGFR inhibitors during metastatic colorectal cancer treatment." (PMID 36083889, 2022). "Activating point mutations of the KRAS proto-oncogene are clinically relevant for many types of cancer, including colorectal cancer (CRC)." (PMID 35200357, 2022). "In a second publication, Jass and coworkers found that mucinous differentiation of colorectal cancers was significantly greater in tumors with KRAS mutations, which is also a frequent feature of CMS36,23." (PMID 34475526, 2022).
colorectal cancer (continued). "Investigations into potentially variable associations of metabolic factors and molecular subtypes of colorectal cancer have been inconsistent, but some reports suggest a possible association between adiponectin and lower risk of KRAS‐mutated colorectal cancer." (PMID 35383926, 2022). "We previously reported rare regressive genetic trajectories of KRAS pathogenic mutations as a specific hallmark of the genuine oligometastatic status in colorectal cancer (CRC)." (PMID 35936004, 2022). "This is the first study in Africa attempting to elucidate the link between fat intake, considering different fat types, and KRAS mutations in colorectal cancer." (PMID 35057499, 2022). "In colorectal cancer, KRAS mutation suppresses Th1/CTL immunity, reducing IFNγ and CXCL10 production, therefore decreasing CTL infiltration." (PMID 36311166, 2022). "In some cases, recommendations were given that were clearly not indicated, such as the administration of anti-EGFR substances in KRAS-mutated colorectal carcinoma." (PMID 34436668, 2022). "In patients with colorectal carcinoma metastasis, KRAS and NRAS mutations are tested prior to anti-epidermal growth receptor (EGFR) target therapy, as mutated RAS proteins downstream of EGFR will impair treatment effectiveness." (PMID 35328664, 2022). "The combination was tested in vivo in seven patient-derived xenograft (PDX) models (five colorectal carcinoma and two papillary thyroid carcinoma models) with different KRAS, BRAF, and NRAS mutations." (PMID 35075200, 2022). "Recently, DHX38/PRP16 has been implicated in the proliferative potential of the HCT116 colorectal carcinoma cell line, where cells harboring an active KRAS mutant become responsive to DHX38/PRP16 knockdown." (PMID 34965029, 2022). "KRAS gene mutations are a well-investigated mutation in several carcinomas such as melanoma, non-small-cell lung carcinoma, colorectal carcinoma, and papillary thyroid cancer." (PMID 35782059, 2022). "In the present study, we aimed to determine the association between fat intake and the prevalence of KRAS mutations at codons 12 and 13 of exon 2 in colorectal carcinomas." (PMID 35057499, 2022). "~50% of colorectal cancers have an activating mutation in KRAS (encoding the KRAS proto-oncogene) and remain difficult to target in the clinic." (PMID 33855169, 2021). "Here, we demonstrate that oncogenic KRAS mutations upregulate the expression of selected amino acid transporters in colorectal cancer (CRC) cells through the hippo signaling effector YAP1." (PMID 34003553, 2021). "Due to this, downstream signaling in G13D-mutated cells is extremely RTK-dependent, possibly explaining why KRASG13D-mutated colorectal cancers are sensitive to EGFR-TKIs while other KRAS-mutated colorectal tumors are refractory to EGFR-TKI treatment." (PMID 33924994, 2021). "A further important open issue is targeting non-G12C KRAS mutations; for instance, KRAS G12V mutation, although more common in colorectal cancers (CRC) or pancreatic adenocarcinomas, accounts for about 6% of NSCLC mutations." (PMID 35004317, 2021). "As an oncogene, KRAS mutations were reported frequently in a variety of tumors, including colorectal cancer, pancreatic cancer, and bladder cancer." (PMID 34858994, 2021). "After searching of eligible studies in databases, and subsequent extraction and analysis of data, those techniques (digital PCR, ARMS, and NGS) showed overall high accuracy in detecting KRAS mutation in cfDNA samples of colorectal cancer patients." (PMID 33770081, 2021). "Lung, pancreatic, and colorectal cancers remain being the most lethal cancers in the United States with high mutation rates in KRAS, the most commonly mutated isoform." (PMID 34504197, 2021).
colorectal cancer (continued). "KRAS mutations have also been associated with increased TF expression levels in colorectal cancer and NSCLC." (PMID 33996610, 2021). "The three RAS genes are mutated in 45% of all colorectal cancer cases, where KRAS is the most frequently mutated RAS isoform." (PMID 33801965, 2021). "High levels of vitamin C have been found to selectively kill colorectal cancer cells harboring KRAS or BRAF mutations." (PMID 33777798, 2021). "Recently, it was demonstrated that metabolic adaptions play an important role in highly resistant colorectal cancers with KRAS (Kirsten rat sarcoma 2 viral oncogene homologue) mutation." (PMID 34440056, 2021). "A total of 146 colorectal cancer samples were sent to Nantes University Hospital between 1 January and 31 December 2019, to test for KRAS, NRAS or BRAF mutations by NGS and microsatellite instability by MSI-PCR." (PMID 34439357, 2021). "For instance, KRAS is frequently mutated, especially in colorectal cancer and pancreatic adenocarcinoma, wherein 33-61% of the patients carry a KRAS mutation." (PMID 34326838, 2021). "When putting these found mutations into a clinical perspective, only KRAS mutations are currently of primary influence in colorectal cancer patients, as these are predictive for cetuximab and panitumumab therapy success." (PMID 34065112, 2021). "Approximately 30–40% of colorectal cancers (CRC) harbor activating mutations in Kirsten Ras (KRAS) proto-oncogene, which encodes for a GTPase transductor protein downstream of epidermal growth factor receptor (EGFR) as part of the RAS/RAF/MAPK pathway." (PMID 34108518, 2021). "KRAS is a gene that is commonly mutated in cancer, especially in pancreatic, lung and colorectal cancers." (PMID 33466360, 2021). "KRAS is mutated in ∼90% of pancreatic ductal adenocarcinomas, ∼35% of colorectal cancers and ∼20% of non-small-cell lung cancers." (PMID 33130216, 2021). "Mutations in this gene play an equivalent role as KRAS mutations in chromosomal instability colorectal cancer." (PMID 35118001, 2021). "Several studies have reported that the prognostic effect of KRAS mutations on colorectal cancers (CRCs) varies depending on the type of mutation." (PMID 34272423, 2021). "KRAS is usually mutated in colorectal cancers, and the KRAS and TGF pathways are responsible for tumor progression." (PMID 33996604, 2021). "KRAS gene G12/13 mutation has also been found in ucfDNA by the NGS approach of patients with colorectal cancer." (PMID 34071230, 2021). "In a series of 13336 colorectal cancers, p.V14 was identified as a KRAS mutation hotspot and p.V14 mutations have previously been associated with a range of RASopathies, supporting our finding that KRAS p.V14 mutations are rare but oncogenic." (PMID 34313788, 2021). "Some studies have demonstrated that KRAS gene mutated colorectal cancers were correlated with worse overall survival." (PMID 33784337, 2021). "In colorectal cancer, KRAS mutations in cluster 9458.0 affecting p.G12, p.G13, p.V14, and p.Q61 are associated with higher KRAS expression, whereas HNF4A mutations in cluster 7977.0 are associated with low HNF4A expression." (PMID 33875650, 2021). "in 2018, where the researchers introduced indels using the CRISPR/Cas9 system, causing frameshift mutations at the KRAS codon-12 sites using colorectal cancer cells (SW480, SW620, SNU407, AS-PC1 cell lines)." (PMID 34781949, 2021). "When the patients were categorized with the cancer antigen markers, patients with advanced colorectal cancer had more frequent KRAS and PTEN mutations." (PMID 35003350, 2021). "In summary, the results of this work suggest that patients with a combination of wild-type PIK3CA and mutated-KRAS tumors in particular benefit from aspirin use after diagnosis of colorectal cancer." (PMID 34638442, 2021).
colorectal cancer (continued). "An association between activating mutations in KRAS and resistance to ICIs has also been reported in colorectal cancer." (PMID 34359568, 2021). "Prognostic data on aspirin use after diagnosis of colorectal cancer in relation to KRAS mutational status is limited." (PMID 34638442, 2021). "In concordance with our results, the pharmacologic ascorbate treatment of KRAS mutant colorectal cancer cells caused the dramatic downregulation of GLUT1." (PMID 33925206, 2021). "Oncogenic KRAS mutations are commonly found in colorectal cancers (40–50%), making it the most prominently mutated proto-oncogenes known to date." (PMID 33959410, 2021). "The main objective of the study was to determine the effect of the presence of mutation in the KRAS gene on the survival in patients with colorectal cancer (CRC) and peritoneal metastases (PM)." (PMID 34557315, 2021). "The aim of this systemic review and meta-analysis was to investigate the accuracy of those methods in detecting KRAS mutation in cell-free DNA sample from patients with colorectal cancer." (PMID 33770081, 2021). "To define the capacity of colorectal cancer organoids to mirror the genome heterogeneity of the corresponding patient tumor, we compared the mutational status of three genes (KRAS, NRAS, and BRAF) in 19 PDTOs and corresponding tumor tissues." (PMID 34359661, 2021). "We used TOF‐SIMS to identify important metabolites and oncogenic KRAS mutation expressed in human colorectal cancer (CRC)." (PMID 34027089, 2021). "Before anti-EGFR therapy is given to patients with colorectal cancer, it is required to determine KRAS mutation status in tumor." (PMID 33770081, 2021). "Colorectal cancer cells with KRAS or BRAF mutations show enhanced glucose metabolism such as glucose uptake and glycolysis, and require expression of glucose transporter-1 (GLUT-1), a membrane glucose transporter." (PMID 33420213, 2021). "KRAS is mutated in 35–45% of colorectal cancers (CRC), and an additional 5–10% of cases harbor mutations in the NRAS oncogene; alterations in HRAS in CRC are very rare." (PMID 34063999, 2021). "KRAS MASI is associated with worse prognosis in colorectal cancer and pancreatic cancer and loss of the WT KRAS allele has been found at a higher rate in metastatic KRAS-mutated lung and pancreatic cancers compared to the primary tumors." (PMID 33924994, 2021). "In this context, LAT1 is required for efficient growth of KRAS-mutant colorectal cancer, and rapamycin reduces LAT1-deficient cell proliferation and tumor formation, suggesting LAT1 as an attractive therapeutic target for various cancers." (PMID 34194623, 2021). "CT image texture parameters of colorectal cancer have certain correlation with KRAS/NRAS/BRAF gene mutations in colorectal cancer, and the texture parameters extracted from MRI images can help predict TCGA/TCIA molecular subtypes in breast cancer." (PMID 34307164, 2021). "In KRAS mutated colorectal cancer lines TGF-β secretion was required for Treg cell differentiation as mediated via the MEK/ERK/AP-1 pathway." (PMID 33777798, 2021). "In solid tumors including PDAC and colorectal cancer, KRAS mutation was reported to induce tumor-promoting TME by inducing regulatory T-cell differentiation or recruiting MDSCs." (PMID 35087839, 2021). "Mutations that result in the constitutive activation of KRAS signaling (KRAS proto-oncogene signaling) are present in nearly half of all colorectal cancers (CRCs), with these patients responding poorly to current treatments." (PMID 33855169, 2021).